CXCR5 (C-X-C motif chemokine receptor 5)
Diseases named in the same sentence as CXCR5 in open-access papers (continued):
Sharing a sentence is not in itself a finding about the gene and the disease.
pancreatic cancer (11 papers, 2008 to 2025). "For example, overexpression of ETV4 has been shown to activate the CXCL13/CXCR5 axis, promoting pancreatic cancer metastasis, and ETV4 expression serves as an independent prognostic factor influencing patient survival." (PMID 40469297, 2025). "highlighted in their study that CXCL13 plays a significant role in promoting the recruitment of disseminated pancreatic cancer cells expressing CXCR5 to the liver, thereby inducing the growth of liver metastases." (PMID 38343537, 2024). "In pancreatic cancer, which shares many similarities with BTC, high expression of CXCR5 was observed in human pancreatic cancer cell lines as well as human tissue samples." (PMID 36077611, 2022). "A constitutive activation of the noncanonical NF-kB pathway, which was observed in different models of pancreatic cancer, might thus result in a autocrine promigratory cytokine loop through the activation of CXCR5." (PMID 36077611, 2022). "The overexpression of CXCR5 in pancreatic cancer is a potential therapeutic target." (PMID 33169793, 2020). "Human pancreatic carcinoma cell lines express CXCR5, and this GPCR can be detected in a significant proportion of human pancreatic tumors." (PMID 31354634, 2019). "In colorectal and pancreatic cancer, CXCR5+ CD8 T cells arise and respond to cancer cells suggesting a prevalent role for chronic antigen exposure in the development of tumor-specific CXCR5+ CD8 T cells." (PMID 31275308, 2019). "Other examples include T cells engineered to express the chemokine receptor CXCR5 to improve migration in CXCL13 rich lung as well as head and neck cancer microenvironments, and CXCR6 expression that improved migration and function in hypoxic CXCL16-rich pancreatic tumor milieus." (PMID 41181132, 2025).
hepatocellular carcinoma (10 papers, 2015 to 2024). A malignant tumor that arises from hepatocytes. "In hepatocellular carcinoma, CXCR5+CD8+ T cells were frequently PD‐1‐positive and possessed higher proliferation and cytolytic capacities compared to those of CXCR5−CD8+ T cells." (PMID 38069525, 2023). "In hepatocellular carcinoma, follicular lymphoma, thyroid and high-grade serous ovarian cancer, PD-1 is upregulated on CXCR5+CD8 T cells while TIM3 and CTLA4 are downregulated compared to CXCR5−CD8 T cells possibly indicating a Tpex versus Tex phenotype." (PMID 36314014, 2022). "Circulating CXCR5+ CD8 T cells isolated from patients with HBV-related hepatocellular carcinoma and diffuse large B cell lymphoma expressed granzyme B and CD107a that likely contributed to tumor cell and B cell lysis." (PMID 31275308, 2019). "Whereas, in HBV-related hepatocellular carcinoma, viral responses may initially induce CXCR5+ CD8 T cells that then target cancer cells." (PMID 31275308, 2019). "Elevated CXCL13 and CXCR5 expression has also been described in hepatocellular carcinoma (HCC) and was suggested to promote cancer growth through the Wnt/ß-catenin pathway." (PMID 36077611, 2022). "Elevated percentages of CXCR5+CD8+ T cells are reported in the circulation or in the tumor tissues of B cell lymphoma, hepatocellular carcinoma, colorectal cancer, and pancreatic cancer patients." (PMID 38069525, 2023). "The present study reveals an immunological characterization of circulating and tumor-infiltrating T follicular helper cells (Tfh), namely CXCR5+CD45RA−CD4+ T cells, and their related cytokines in hepatitis B virus-related hepatocellular carcinoma (HCC) patients." (PMID 26517519, 2015).
malaria (10 papers, 2015 to 2025). Malaria is a serious and sometimes fatal disease caused by a parasite that commonly infects a certain type of mosquito which feeds on humans. "However, in human, there is only one published report in malaria caused by P. falciparum, demonstrating that circulating PD-1+CXCR5+CD4+ T cells from patients have characteristics of GC Tfh cells, and our study represents the first report of an increase in Tfh cells following P. vivax infection." (PMID 28700710, 2017). "“Hybrid Th1/Tfh” or “Th1-like Tfh” have been used to describe any IFN-γ+ CD4 T cell also expressing IL-21 and/or CXCR5, functional markers of Tfh in Malaria models." (PMID 40356908, 2025). "Consistent with the emergence of Tr1 cells from Th1 subsets, the majority of Tr1 cells where Th1-like (CXCR3+/CCR6-/CXCR5-/FoxP3-) at day 0 during malaria (median 65.4%, IQR 62.5-73.8%)." (PMID 37968278, 2023). "GC-TFH cells are essential for host survival during experimental malaria and their development proceeds via a step-wise process involving upregulation of PD-1, CXCR5, and Bcl6 expression that culminates with the localization of GC-TFH cells in the germinal center." (PMID 33529242, 2021). "In support of this hypothesis, a recent survey of Tfh cell responses in Plasmodium falciparum-exposed children revealed that a phenotypically and functionally distinct T helper 1 (Th1)-like Tfh cell subset (CXCR3+ CXCR5+PD-1+) is preferentially expanded during human malaria." (PMID 27732671, 2016). "Moreover, in an independent experiment (n = 10 Malian children) T-bethi B cells of malaria-exposed children expressed markers that are known to be associated with atypical MBCs, with higher surface expression of FCRL5, CD11c, CXCR3 and CD95, and decreased expression of CD35, CD40, CXCR5 and CCR7." (PMID 28953967, 2017). "We, therefore, examined the signature genes associated with cluster 10 and found enrichment of the transcription factor TCF1 (gene name Tcf7); this has been associated with circulating TFH cells in a mouse model of malaria, but we found no significant enrichment for PD1, CXCR5, or BCL6." (PMID 40214640, 2025).
Arthritis (9 papers, 2017 to 2025). Inflammation of a joint. "SLE patients revealed low SLEDAI score, less myositis, fever, alopecia, vasculitis, arthritis, oral ulcer, and decreased number of CXCR5+PD-1+CCR7lo Tfh cells, CCR6+CXCR3-CCR4+CCR7lo Th17 cells." (PMID 38164134, 2023). "CCR4, CCR6, CCR7, CCR9, CXCR5, and CXCR6 deficiency ameliorated arthritis in CIA mice by suppressing the migration of Th17 cells (CCR4), DC (CCR7), and CD11b+ splenocytes (CCR9)." (PMID 36860872, 2023). "In this sense, we observed a higher proportion of CXCR5+ T cells in the lymph nodes of p110α−/−ΔT in the pre-arthritis stage and an increased expression of the surface markers ICOS, CXCR5 and CD44 in T-cell blasts of p110α−/−ΔT mice." (PMID 34203838, 2021). "Using this model we provide strong evidence for an indispensable role of CXCR5 expression on T cells in autoimmune Ab responses and arthritis development." (PMID 28827539, 2017). "We considered whether the higher number of cells observed in p110α−/−ΔT mice in pre-arthritis stage could be due to an increased expression of homing surface markers, such as CXCR5 and CD44, in activated T cells of p110α−/−ΔT mice." (PMID 34203838, 2021). "Similar to this evidence, it is possible that our observation of reduced populations of CXCR5+Tfh cells seen in the BBR group compared to the CIA and PBS controls contributed to a lower incidence of arthritis as well." (PMID 33805383, 2021). "Chimeric mice harboring Cxcr5-proficient and Cxcr5-deficient immune cells revealed SLO and not the synovial tissue as the compartment where CXCR5-mediated cell migration induces autoimmune inflammation in arthritis." (PMID 28827539, 2017). "Based on CXCR5 and CCR6 internalization and B-cell migration experiments, our results suggest that CXCL13 and CCL20, the respective ligands of CXCR5 and CCR6, by acting synergistically, might participate in the recruitment of B cells in the synovium in patients with arthritis." (PMID 29880013, 2018).
chronic lymphocytic leukemia (9 papers, 2008 to 2023). "For instance, CXCR3 and CXCR5 are traditionally associated with being involved in the migration of activated T-cells and are seldom used to identify B-cell subsets, although they can be expressed on chronic lymphocytic leukemia (CLL) affected B-cells." (PMID 28674539, 2017). "Another study found that chimeric antigen receptor‐T (CAR‐T) cells targeting CXCR5 can remove tumor cells with high CXCR5 expression from B cell follicles of lymphoid organs, especially in the treatment of follicular lymphoma and chronic lymphocytic leukemia." (PMID 37382265, 2023). "This idea is supported by the findings of others who observed that, in the case of chronic lymphatic leukaemia, CXCR5 and its ligand were overexpressed in malignant B cells but that CXCR5 was downregulated after stimulation with soluble CXCL13." (PMID 18781150, 2008). "Specifically in chronic lymphocytic leukemia, in which PD‐1 ICB does not induce clinical responses, CXCR5+PD‐1+ CD8 T cells show loss of the memory phenotype and increased effector differentiation." (PMID 33098668, 2021). "Moreover, CXCL13/CXCR5 has been demonstrated to induce significant resistance to TNF-α-mediated apoptosis in B cell lineage acute and chronic lymphocytic leukemia (B-ALL and B-CLL)." (PMID 34947813, 2021).
Cognitive impairment (9 papers, 2014 to 2025). Abnormal cognition is characterized by deficits in thinking, reasoning, or remembering. "Besides, GABA+ levels in the NMOSD‐CI group were negatively correlated with the frequency of CD4+CXCR5+ T cells, suggesting the underlying coupling mechanism between immune responses and neurotransmitter metabolism in cognition impairment in NMOSD patients." (PMID 38383066, 2024). "Of note, both VEGF-A and CXCL13 are known inducer of BBB disruption while CXCR5, the receptor for CXCL13, is linked to hippocampal neuroinflammation and cognitive impairment in animal models of sepsis and surgery." (PMID 41219650, 2025). "Results from the present study suggest that CXCR5 contributes to cognitive impairment by enhancing p38MAPK/NF-κB/STAT3 signaling." (PMID 34711216, 2021). "Expression of CXCL13 and CXCR5 is altered in intractable temporal lobe epilepsy patients and epileptic rats that show neurodegeneration and cognitive impairment." (PMID 33161894, 2020). "Inhibition of either CXCL13 or CXCR5 effectively rescues post-operative cognitive deficits." (PMID 40914484, 2025). "In the current study, we examined whether down-regulating CXCR5 could alleviate cognitive deficits induced by sepsis by regulating autophagy in hippocampus." (PMID 34711216, 2021). "The present study used a mouse model of SAE to examine whether CXCR5 down-regulation could attenuate cognitive deficits." (PMID 34711216, 2021). "Our results suggest that CXCR5-mediated dysregulation of autophagy may also contribute to cognitive deficits in SAE." (PMID 34711216, 2021). "Our data clearly demonstrate that surgical intervention induced CXCL13 release and an increase in CXCR5 expression followed by cognitive impairment as observed in behavioral tests, and that inhibition of CXCL13/CXCR5 signaling attenuated surgery-induced cognitive impairment." (PMID 33161894, 2020). "Further research into the regulation of NSC/NPC activity should consider investigation of CXCR5 and other chemokines which may be relevant to the pathophysiology of psychiatric disorders including depression, anxiety and cognitive impairment/dementia." (PMID 24528805, 2014). "In contrast, abnormal psychological behaviors, cognitive impairments, serum LDH, serum calcium, CSF glucose, serum oligoclonal bands (OCBs), CD4+ICOS+, CD4+CXCR5+ICOS+, CD19+PD-L1+, and plasma sICOSL were more prominent in the early AE group." (PMID 40352922, 2025). "Knockout of CXCL13 or CXCR5 suppresses ERK phosphorylation and mitigates surgery-induced cognitive impairment." (PMID 40914484, 2025). "CXCR5 knockout further enhanced autophagy but partially reversed all the other CLP-induced effects, including cognitive deficits." (PMID 34711216, 2021). "The downregulation of CXCR5 serves to reinstate autophagy, shift microglia towards an M2 phenotype, and suppress p38MAPK/NF-κB/STAT3 signaling, ultimately mitigating sepsis-induced neuroinflammation and cognitive deficits." (PMID 38298892, 2024). "Recombinant CXCL13 induced cognitive deficits and increased the expression of phospho-ERK as well as IL-1β and TNF-α in hippocampus of wild-type mice, but not CXCR5−/− mice." (PMID 33161894, 2020).
HIV-1 infection (9 papers, 2009 to 2023). The type species of lentivirus and the etiologic agent of acquired immunodeficiency syndrome (AIDS). "CXCR5+PD-1++ CD4+ T cells were the most susceptible to HIV-1 infection (81%) compared to other subsets (second row, far right panel)." (PMID 26034905, 2015). "We now know that characteristic increases in germinal centers (GC) in lymphoid tissue (LT) during SIV and HIV-1 infections are associated with an increase in CXCR5+PD-1high Tfh, which expand to a large proportion of memory CD4+ T cells in LT, and are presumably specific for SIV or HIV epitopes." (PMID 28553284, 2017). "Therefore, the increase in the number of CXCR5+PD-1++ TFH cells is probably due to the activation caused by HIV-1 infection, which leads to their proliferation." (PMID 26034905, 2015). "In untreated HIV-1 infection, CXCR5+ CD4+ T-cell subsets have been shown to contain 11- to 66-fold more HIV-1 RNA than CXCR5− subsets." (PMID 28194154, 2017). "Our study shows that CXCR5+PD-1++ CCR5+ TFH cells were the most permissive CD4+ T cell subset to HIV-1 infection and correlated with the expression of cell surface markers PD-1, CCR5, and CXCR3." (PMID 26034905, 2015). "Altogether, CXCR5+CCR5− CD4 T cells that regulate humoral immunity are allowed greater freedom to operate and expand during HIV-1 infection, but at the same time can contain HIV DNA at levels at least as high as in other CD4 subsets." (PMID 28553284, 2017). "The identification of CXCR5+PD-1++ TFH cells in the gut and FRT of humanized DRAG mice prompted us to evaluate this mouse as an in vivo model for HIV-1 infection." (PMID 26034905, 2015). "We have recently shown that during chronic HIV-1 infection, CD27+ and CD27− B-cells show an altered migration patterns due to alterations in expression of the receptor-ligand pair CXCR5/CXCL13." (PMID 19412542, 2009). "Although follicular cytotoxic T cells (Tfcs) expressing CXCR5 were identified in lymph node BCF during chronic SIV/HIV-1 infection, Tfcs do not express CXCR5, have weak cytotoxicity, and appeared to be non-HIV-1 specific." (PMID 37936122, 2023). "(2016) found that during untreated HIV-1 infection, T-cells expressing HIV-1 RNA and Gag protein were enriched particularly in T-cells expressing PD-1 and Tfh cell markers (PD-1+CXCR5+), with additional enrichment in cells co-expressing PD-1 with other immune checkpoint markers (TIGIT+ and CTLA-4+)." (PMID 36776833, 2023).
sarcoidosis (9 papers, 2020 to 2025). Sarcoidosis is a multisystemic disorder of unknown cause characterized by the formation of immune granulomas in involved organs. "Current study demonstrates that there is an elevated presence of CXCR5+ CM Th cells in individuals with sarcoidosis." (PMID 41376646, 2025). "In contrast, the frequencies of Tfh1 within EM CXCR5+ CD4+ T cells were significantly lower in both groups of patients with sarcoidosis compared and healthy controls, while Tfh2 and Tfh17 cells were significantly elevated." (PMID 41376646, 2025). "Primarily, we found that CXCR5 expression increased in CM Treg cell subsets in patients with sarcoidosis (25.99% (20.34; 30.76) vs. 16.67% (13.73; 21.74) with p < 0.001)." (PMID 37189479, 2023). "Next, we demonstrated that the balance of CD45RA−CCR7+ CXCR5+ Tfh subsets is altered in patients with sarcoidosis." (PMID 31974463, 2020). "Next, a significantly higher proportion of CXCR5-expressing CD45RA − CCR7+ Th cells in patients with sarcoidosis in comparison to the healthy controls was revealed, that represents the expansion of this memory Th cell subset in the disease." (PMID 31974463, 2020). "We also noted a statistically significant increase in central memory CXCR5+CCR6–CXCR3– follicular Th cells, as wells as effector memory CXCR5+CCR6–CXCR3– and CXCR5+CCR6+CXCR3– follicular Th cells in both groups of patients with sarcoidosis vs. healthy controls." (PMID 41376646, 2025). "In this study, we compared blood‐borne signatures of these two diseases and found that both are characterised by inflammatory monocytes and transcriptional signatures of epithelial–mesenchymal transition, but CXCR5 down‐regulation occurs in TU, while sarcoidosis appears to be antigen‐driven." (PMID 40469525, 2025). "Finally, we found that CXCR5 expression was increased in CM Tregs cell subsets in patients with sarcoidosis." (PMID 37189479, 2023). "When comparing B and Tfh cell counts in patients with sarcoidosis, it was found that the level of B cells and CD4 + CXCR5+ T cells was significantly higher in lymph node biopsy compared to BALF and peripheral blood sample." (PMID 38179278, 2023). "Down‐regulation of CXCR5 was also observed on B cells in patients with active TU but not in those with quiescent disease or in sarcoidosis, supporting the former explanation." (PMID 40469525, 2025). "TU is distinguished from sarcoidosis because failure to upregulate CXCR5 means that migration of liberated cells does not involve lymph nodes." (PMID 40469525, 2025). "Unlike sarcoidosis, active TU is characterised by marked CXCR5 down‐regulation on B cells and CD4+ T cells that normalises on remission." (PMID 40469525, 2025). "There was no expansion of CXCR5− PD‐1+ CD4+ T cells in active sarcoidosis compared with healthy controls." (PMID 40469525, 2025). "The proportion of Tfh cells (CD4+CXCR5+PD1+) which are closely correlated with the differentiation and maturation of B cells increased significantly in the peripheral blood of patients with active sarcoidosis as compared to patients with stable sarcoidosis and healthy controls." (PMID 32508842, 2020). "In contrast, additional phenotyping of CD4+CD45RA- memory T cells demonstrated an expansion of CXCR5-expressing T follicular helper (TFH)-like cells with a significant increase of CXCR3-expressing TFH1-like cells and a decrease of CCR6-expressing TFH17-like cells when compared to sarcoidosis." (PMID 33613543, 2020). "We also observed down‐regulation of CXCR5 on CD19+ B cells in patients with active TU, while there was no such reduction in inactive TU, sarcoidosis or healthy controls." (PMID 40469525, 2025). "CXCR5 was upregulated in sarcoidosis Tregs and CD8+ cells, but CD4+CXCR5+ T follicular helper cell numbers were not affected." (PMID 38173720, 2023).
sarcoidosis (continued). "Analyzing circulating Tfr cells in patients with sarcoidosis showed that within the total CD45RA–CCR7+ central memory Treg population, the proportion of CXCR5+ Tregs was increased, whereas the percentage of thymic CXCR5+ Tregs did not significantly differ from that in the control group." (PMID 38179278, 2023).